ENSG00000287725 (novel protein, TPCN2 - SMIM38 readthrough)
Gene: Protein-coding gene on chromosome 11 (69,072,915 to 69,162,440, forward strand). Ensembl gene ENSG00000287725.
Genetic constraint (gnomAD): Missense variants: 497 observed, 481.54 expected, observed/expected ratio (o/e) 1.03, 90% interval 0.96 to 1.11. Synonymous variants: 187 observed, 196.71 expected, observed/expected ratio (o/e) 0.95, 90% interval 0.84 to 1.07.